BRAF (B-Raf proto-oncogene, serine/threonine kinase)
Diseases named in the same sentence as BRAF in open-access papers (continued):
Sharing a sentence is not in itself a finding about the gene and the disease.
urothelial carcinoma (29 papers, 2016 to 2026). A malignant neoplasm derived from the transitional epithelium of the urinary tract (urinary bladder, ureter, urethra, or renal pelvis). "For example, single gene-based assays have been available for years for diagnosing KIT mutations in mast cell tumors (MCTs), while assays for BRAF mutations in urothelial carcinomas have just been identified." (PMID 40616061, 2025). "Urothelial carcinoma (UC) is a common cancer in dogs, and detection methods beyond cytology, histology, and testing for a BRAF mutation are needed." (PMID 40711281, 2025). "In approximately 80% of cases of canine urothelial carcinoma (UC), the mutation V595E in the BRAF gene is present." (PMID 40872680, 2025). "Although no studies have been published about its efficacy in canine tissue to date, it is worth noting that the manufacturer’s website features an image of a canine BRAF-mutated urothelial carcinoma stained with their antibody." (PMID 39591358, 2024). "Urine samples from dogs diagnosed with urothelial carcinoma were tested, and conventional PCR was used to detect both the wild-type (Wt) and mutant (Mu) BRAF V595E mutation in the urine samples, with GAPDH serving as an internal control." (PMID 39272320, 2024). "Molecular profiling studies have shown that 85% of canine urothelial carcinomas (UC) harbor an activating BRAF V595E mutation, which is orthologous to the V600E variant found in several human cancer subtypes." (PMID 37079639, 2023). "ERBB2 and BRAF are the most frequently mutated genes in pulmonary adenocarcinoma and urothelial carcinoma, mutated in 50% and 40% of the samples respectively." (PMID 37414794, 2023). "In dogs, detection of BRAF V595E mutation is typically carried out by PCR testing and is primarily used as a diagnostic marker to detect carcinomas of the urinary tract or prostate." (PMID 37570213, 2023). "Previous studies have described a somatic point mutation in the BRAF gene (BRAFV595E) in canine urothelial carcinoma cells, and detection of this mutation can be used as a diagnostic aid." (PMID 35203195, 2022). "The specific BRAF gene mutation was also investigated in dogs with urothelial carcinomas since it had been shown that nearly 80% of these tumours in dogs have a mutation in this gene." (PMID 35815441, 2022). "The detection of BRAF mutations in urine-derived cells is also widely used as a method to support the diagnosis of urothelial carcinoma in dogs." (PMID 35203195, 2022). "Recently, 80% of canine urothelial carcinoma was reported to have the BRAF V595E mutation, which is homologous to the human V600E mutation." (PMID 34502061, 2021). "Recent studies have reported that up to 80% of canine urothelial carcinoma has the BRAF V595E mutation, which is homologous to the human V600E mutation." (PMID 34502061, 2021). "Further research is required to establish the true clinical value of plasma mutated BRAF ctDNA as a biomarker for canine urothelial carcinoma." (PMID 32330187, 2020). "Recently, studies have reported that the canine BRAF V595E mutation, a single nucleotide T to A transversion at nucleotide 1349, is detectable in 80% of canines with urothelial carcinomas." (PMID 32330187, 2020). "Our results show that BRAF-mutated ctDNA can be detected using allele-specific real-time PCR in plasma samples of canines with urothelial carcinoma with the BRAF V595E mutation." (PMID 32330187, 2020). "The aim of this study is to measure the BRAF-mutated ctDNA levels in plasma and to assess its clinical significance in canines with urothelial carcinoma." (PMID 32330187, 2020). "In conclusion, our results show that mutated BRAF ctDNA can be detected using allele-specific real-time PCR in plasma samples of canines with urothelial carcinoma harboring the BRAF V595E mutation." (PMID 32330187, 2020).
urothelial carcinoma (continued). "In veterinary medicine, testing for the presence of the BRAF mutation using urine or tissue samples is a sensitive and noninvasive method for the diagnosis of canine urothelial carcinoma." (PMID 32330187, 2020). "This study investigates the BRAF V595E allele concentration in circulating cell-free DNA (cfDNA) and assesses the clinical significance of BRAF-mutated ctDNA levels in canines with urothelial carcinoma." (PMID 32330187, 2020). "Interestingly, BRAF proto-oncogene mutations represent the main oncogenetic mechanism in canine urothelial carcinoma models and have long been implemented as a veterinary biomarker for BC." (PMID 40002790, 2025). "Moreover, recent empirical evidence, albeit scarce, has seemingly implicated BRAF gene mutations in the carcinogenesis of urothelial carcinomas in humans as well." (PMID 40002790, 2025). "In canine urothelial carcinoma, the BRAF gene is frequently mutated (V595E)." (PMID 37570213, 2023). "Detection of mutated BRAF cfDNA in plasma may be a potentially useful biomarker for noninvasive follow-up of canines with urothelial carcinoma." (PMID 32330187, 2020). "We found that the ctDNA concentration in patients with BRAF-mutated urothelial carcinoma is increased compared to that in wild-type patients, demonstrating that the BRAF mutation in urothelial carcinoma may be detectable in the plasma of these canines." (PMID 32330187, 2020). "Recently, BRAF V595E mutation has been reported in 80% of dogs with urothelial carcinoma." (PMID 32330187, 2020). "Thus, the authors suggest that the amount of ctDNA with BRAF mutations may represent a useful non‐invasive diagnostic biomarker in canine urothelial carcinoma." (PMID 35815441, 2022). "Of these, BRAF-V600E was discovered in a case of conventional urothelial carcinoma pT1aG2, and BRAF-V600L in another case of conventional urothelial carcinoma pT2bG3." (PMID 40002790, 2025). "These mutations are enriched in carcinoma, with significant enrichment of BRAF V558E in urothelial carcinoma (p = 3.92 × 10−14) and BRAF V695E in pulmonary adenocarcinoma (p = 3.52 × 10−8)." (PMID 37414794, 2023). "Furthermore, it is possible that ctDNA in plasma of the dog could be indicative of a BRAF mutation originating from other neoplasms that have been undiagnosed because BRAF V595E mutation has been detected in not only urothelial carcinoma but also many other neoplasms." (PMID 32330187, 2020). "On the one hand, KRAS and BRAF mutations occurred in UrC with similar frequencies as in CRC, in contrast to urothelial carcinoma, where both of these mutations are infrequent." (PMID 27283768, 2016). "Third, BRAF mutation testing was not consistently performed in all clinical cases with suspected urothelial carcinoma, although diagnoses were based on imaging findings, cytologic evaluation, and clinical presentation." (PMID 40960428, 2025). "The BRAF V595E mutation analysis in canine urothelial carcinomas (UCs) has found its way into routine diagnostics, but no data analysis has been published until now." (PMID 40872680, 2025). "Given that homologous encoding somatic mutations (i.e., BRAF p.V595E) are highly recurrent in some tumors of dogs, including papillary OSCC and urothelial carcinoma, VE1 IHC might be a useful tool that would complement RAS Q61R-specific SP174 antibody IHC." (PMID 37901104, 2023). "Similarly, our study identifies BRAF V588E (equivalent to V600E in humans) in 35% urothelial carcinomas, lower than several publications." (PMID 37414794, 2023). "Each 5 urothelial carcinoma (UC) cell lines with and without the v-Raf murine sarcoma virus oncogene homolog B (BRAF) gene mutation (V595E) were established and examined V595E-related tumorigenic characteristics in dogs." (PMID 36477686, 2022).
urothelial carcinoma (continued). "Recent studies have identified the canine BRAF V595E mutation (cBRAF reference sequence ENSCAFT00000006306), which is homologous to the human BRAF V600E mutation, in several canine cancers and at least 80% of canine urothelial carcinoma." (PMID 32330187, 2020). "BRAF mutations were found to be absent in urothelial carcinoma, while, to best of our knowledge, there are no available data on the occurrence of its mutations in primary ADC of the bladder." (PMID 27283768, 2016). "This study suggests that the quantification of mutated BRAF ctDNA in plasma may represent a useful biomarker for the noninvasive diagnosis of canine urothelial carcinoma when the tumor has the BRAF mutation." (PMID 32330187, 2020). "We report a unique clinical case where anti-BRAF/MEK therapy for BRAF-V600E-positive MM appeared to coincide with the emergence and progression of urothelial carcinoma, suggesting potential implications for these agents in bladder tumorigenesis." (PMID 40002790, 2025).
glioneuronal tumors (28 papers, 2015 to 2026). "The rare KIAA1549:BRAF ex13:ex11 fusion variant was only described in one case of spinal glioneuronal tumor." (PMID 36163281, 2022). "Among the low grade glial or glioneuronal tumor cohort, all selected cases with BRAF V600E mutation (5/5) or FGFR1 N546K or K656E mutation (5/5) evaluated by HRM-sequencing were also detected with the mdPCR assays." (PMID 33282733, 2020). "As seen in other glioneuronal tumors, BRAF V600E mutations and FGFR1 alterations (including FGFR1 germline mutations) have been reported in up to 30%–80% of the tumors depending on the composition of the tumor cohort analyzed." (PMID 31181803, 2019). "Genetic alterations associated with glioneuronal tumors include BRAF mutations and oncogenic fusions." (PMID 29872694, 2017). "These aberrations ranging from hotspot mutations such as BRAF V600E and oncogenic fusions like BRAF–KIAA1549 are particularly enriched in gliomas and glioneuronal tumors, highlighting MAPK signaling as a key oncogenic driver." (PMID 41514664, 2026). "BRAF V600E mutation and further MAPK activating molecular alterations are also frequent events in low-grade glial and glioneuronal tumors." (PMID 36826144, 2023). "Ancillary molecular testing is occasionally helpful in further categorizing such tumors, though this cannot always be relied upon as glial/glioneuronal tumors also frequently harbor overlapping molecular alterations such as BRAF p.V600E." (PMID 36969278, 2023). "The aim of the study was to evaluate the clinicopathological features, as well as the surgical prognosis, of epilepsy-associated glioneuronal tumors (GNT) with CD34 expression and BRAF mutation." (PMID 36307486, 2022). "As with BRAF alterations, these are histologically and spatially enriched, most frequently arising in dysembryoplastic neuroepithelial tumors, other glioneuronal tumors, and in midline brain structures." (PMID 32164789, 2020). "A decade later, mutations in the BRAF gene, the V600E point mutation in particular, have been demonstrated in a range of low-grade IDH-wildtype glial and glioneuronal tumours, and also are increasingly recognised in malignant variants." (PMID 29098416, 2018). "In these conditions, ETV4 would be an interesting marker for screening the CIC fusions in the spectrum of high‐grade glial/glioneuronal tumors, IDH, H3‐ and BRAF‐wildtype." (PMID 39442927, 2025). "To achieve this goal, we evaluated BRAF and FGFR1 mdPCR assays in low grade glial or glioneuronal tumors and H3F3A, IDH1/2 and pTERT mdPCR assays in diffuse gliomas." (PMID 33282733, 2020). "The BRAF and FGFR1 mdPCR assays might particularly be useful in the context of pediatric-type glial or glioneuronal tumors." (PMID 33282733, 2020). "Of note, a series of intramedullary low-grade glioneuronal tumors of the spinal cord in children harboring BRAF fusion and monosomy 1p without diffuse leptomeningeal spread was recently reported." (PMID 29880043, 2018).
metastasis (27 papers, 2014 to 2026). The spread or migration of cancer cells from one part of the body (where they first appeared) to another. "Presence of lung metastasis, BRAF mutation, and log-transformed alkaline phosphatase were the variables selected as predictors in more than 60% (even 80%) of the bootstrap samples." (PMID 32172334, 2020). "In terms of clinicopathological characteristics, SRC mutation was significantly associated with left-sided tumor and liver metastasis compared to BRAF V600E mutation (P = 0.016 and P = 0.025, respectively)." (PMID 30792536, 2019). "Increased EHD2 mRNA expression was significantly associated with extrathyroidal extension (p < 0.001), pT3-4 (p < 0.001), lymph node metastasis (p < 0.001), higher risk of recurrence (p < 0.001), BRAF V600E (p < 0.001), and BRAFV600E-like PTC (p < 0.001)." (PMID 28358874, 2017). "Both the CRP SNP rs7553007 and KRAS/BRAF mutations were independent prognostic factors for CRC patients with synchronous liver metastasis." (PMID 23755178, 2014). "Indeed, recent scientific studies reported that BRAF V600K MMs, in contrast to BRAF V600E MMs, seem to increase with age and have a higher risk for brain and lung metastases and a shorter time from diagnosis to metastasis onset and patient death." (PMID 35080260, 2022). "Among these, NSCLC patients with BRAF mutations had more pleural metastasis (47.1% vs.16.8%, P = 0.005), and NRAS mutations had lung (60.0% vs.12.4%, P = 0.025) and pleural metastasis (60.0% vs.16.8%, P = 0.038)." (PMID 39464712, 2024). "The BRAF mutation testing was negative; therefore, the final diagnosis was cutaneous achromic melanoma with lymph node metastasis, the small-cell type." (PMID 41234990, 2025). "The results showed that the presence of the A-allele at CRP SNP rs7553007 (HR = 1.101; 95% CI = 1.011–1.200; P = 0.027) and KRAS/BRAF mutations (HR = 2.377; 95% CI = 1.293–4.368; P = 0.005) were independent prognostic factors in CRC patients with synchronous liver metastasis." (PMID 23755178, 2014). "Furthermore, the CRP SNP rs7553007 (hazard ratio [HR] = 1.101; 95% confidence interval [CI] = 1.011–1.200; P = 0.027) and KRAS/BRAF mutations (HR = 2.377; 95% CI = 1.293–4.368; P = 0.005) remained predictive for the CSS of CRC patients with synchronous liver metastasis in multivariate analysis." (PMID 23755178, 2014). "Data showed that the TCAF2+ TPC ratio was associated with liver metastasis and TNM stage, but not with KRAS or BRAF mutations." (PMID 37635201, 2023). "This study showed that the MAF of BRAF V600E did not correlate with recurrence or tumor markers or lymph node metastasis, but with tumor diameter." (PMID 34168268, 2021). "Other characteristics of MA/MC in our study, such as higher rates of right‐side (34.8%), poor differentiation (42.6%), RAS‐mutant (43.5%), BRAF‐mutant (7.5%), MSI (5.0%), and the presence of peritoneal metastasis (33.3%), were similar to those reported in previous studies." (PMID 33939281, 2021).
cutaneous squamous cell carcinoma (26 papers, 2012 to 2024). "BRAF inhibitor alone was associated with a 5.2-fold increase in risk of cutaneous squamous-cell carcinoma (13.27% vs. 2.51%) and a higher risk keratoacanthoma (8.97% vs. 1.82%) than the combination of BRAF and MEK inhibitors." (PMID 39776585, 2024). "BRAF inhibitors tend to trigger paradoxical hyper-activation of pERK and induction of neoplasia in the skin, such as cutaneous squamous cell carcinoma, whereby vemurafenib cause such effects more remarkably than dabrafenib or encorafenib." (PMID 35214043, 2022). "The PDV cell line is a mouse keratinocyte bearing HRASQ61L mutation, which is the most relevant mutation in BRAF inhibitor-induced cutaneous squamous cell carcinoma." (PMID 31242703, 2019). "BRAF inhibitor (BRAFi) therapy is associated with the induction of neoplasia, most commonly cutaneous squamous cell carcinoma (cuSCC)." (PMID 27028853, 2016). "Cutaneous squamous cell carcinomas have previously been associated with targeted therapies that inhibit BRAF." (PMID 26370187, 2015). "Overall, BRAF inhibitors were well tolerated; common adverse events are arthralgia, rash, fatigue, alopecia, keratoacanthoma or cutaneous squamous-cell carcinoma, photosensitivity, nausea, and diarrhea, with some variants between different inhibitors." (PMID 22554099, 2012). "The development of hyperkeratosis, a well-known precursor of cutaneous squamous cell carcinomas, was frequent during monotherapy with both BRAF inhibitors." (PMID 39776585, 2024). "Paradoxical MAPK activation is known to be the main reason for cutaneous squamous cell carcinoma induced by BRAF inhibitor in RAS mutant cells." (PMID 31242703, 2019). "Cutaneous squamous cell carcinoma (cuSCC) and keratoacanthoma (KA) develop in approximately 20% to 30% of patients who are treated with BRAF (v-raf murine sarcoma viral homolog B1) inhibitors, such as vemurafenib (PLX4032)." (PMID 31242703, 2019). "The secondary cancers like cutaneous squamous-cell carcinoma, skin papillomas and keratoacanthoma are considered to be the characteristic adverse events of BRAF inhibitor monotherapy, and occur in approximately 14 to 26% of the patients." (PMID 28416755, 2017). "Frequency of cutaneous squamous cell carcinoma and keratoacanthoma is lower in patients treated with the combination of BRAF and MEK inhibitor." (PMID 28374234, 2017). "Of note, tovorafenib appears to have antitumor activity in the setting of BRAF alterations without the clinical manifestations of paradoxical activation seen with type I BRAF inhibitors, such as the development of cutaneous squamous cell carcinoma or keratoacanthoma." (PMID 37219686, 2023). "Classical side effects of BRAF inhibitors include gastrointestinal symptoms (diarrhea, nausea, vomiting), skin symptoms (cutaneous squamous cell carcinoma, keratoacanthoma, photosensitivity reaction, hyperkeratosis, rash), fatigue, pyrexia, and elevated liver enzymes." (PMID 28374234, 2017). "However, most patients relapsed about 7 months after targeted therapy and approximately 14-26% of patients have development of secondary cutaneous squamous cell carcinoma and hyperkeratotic lesions within the first 2-3 months after BRAF inhibition." (PMID 26143635, 2015). "Therapy with BRAF and MEK inhibitors was associated with a lower risk of CAEs, especially rash, alopecia, hyperkeratosis, palmoplantar erythrodysaesthesia syndrome, palmoplantar keratoderma, skin papilloma, cutaneous squamous-cell carcinoma, and keratoacanthoma, compared with BRAF inhibitor alone." (PMID 39776585, 2024). "However, BRAF inhibitors are found to induce cutaneous squamous cell carcinoma (cuSCC)." (PMID 27141983, 2016). "The proportion of patients from the BRAF inhibitor alone treatment group who had a high-grade CAE compared with the BRAF and MEK inhibitor treatment group were 12.81% vs. 2.30% for cutaneous squamous-cell carcinoma and 6.25% vs. 0.68% for keratoacanthoma." (PMID 39776585, 2024).
cutaneous squamous cell carcinoma (continued). "However, non-melanoma skin cancers — well-differentiated cutaneous squamous-cell carcinomas (cuSCC) and keratoacanthomas (KA) — have developed in approximately 11 % to 30 % of patients treated with type I BRAF inhibitors such as dabrafenib and vemurafenib." (PMID 27141983, 2016).